ENSG00000235059 (novel transcript)
Synonyms: LOC101929148; PRY1; PTPN13LY; PRY
Gene: Long non-coding RNA gene on chromosome Y (22,438,924 to 22,514,637, forward strand). Ensembl gene ENSG00000235059.
Diseases named in the same sentence as ENSG00000235059 in open-access papers:
ENSG00000235059 is named in the same sentence as 4 diseases in open-access papers, as found by Europe PMC text mining. Sharing a sentence is not in itself a finding about the gene and the disease.
ENSG00000235059 shares sentences with these, for which no sentence is quoted: cancer (1 paper); fungal infections (1); infection (1); Infertility (1).